FOXO1 (forkhead box O1)
Diseases named in the same sentence as FOXO1 in open-access papers (continued):
Sharing a sentence is not in itself a finding about the gene and the disease.
tumor (continued). "In MM, FOXO1 mediates cell apoptosis and inhibits tumor cell growth." (PMID 37065484, 2023). "FOXO1 transcription was maintained to have a tumor-suppressing effect." (PMID 36292952, 2022). "Furthermore, as a cancer suppressor, reviving the activity of FOXO1 favors the excretion of tumor-infiltrating activated regulatory T (Treg) cells from tumor tissues." (PMID 36290822, 2022). "Together, this data help explain the observed tumor-mediated cardiac dysfunction that is likely related to an upregulation in cardiac inflammation (MyD88) and autophagy (beclin-1) leading to metabolic perturbations and atrophy (p-FOXO1)." (PMID 36531941, 2022). "In addition, FOXO1 has been shown to play a vital role in embryonic development, fat formation, and tumor formation." (PMID 35346026, 2022). "In conclusion, we identified an effective combination therapy involving class I histone deacetylase and mammalian target of rapamycin complex 1/2 inhibition that effectively blocked the EMT of tumor cells by upregulating FoxO1 expression to inhibit Twist1 transcription." (PMID 33772986, 2022). "AR expression or dihydrotestosterone (DHT) treatment can decrease the forkhead box O1 (FOXO1) expression and cause FOXO1 phosphorylation through the protein kinase B signaling pathway, which works as a tumor suppressor to BLCA cells metastasis, migration, invasion, and proliferation." (PMID 36468030, 2022). "Particularly, FoxO1-dependent regulation of macrophage functionality has been recognized to be complicated in multitudinous disease conditions such as infection, metabolic disorders, fibrosis, autoimmune diseases and tumor development." (PMID 35993049, 2022). "Furthermore XBP1-u also exerts its anti-tumor function by promoting FoXO1 degradation, thereby inhibiting tumor cells autophagy." (PMID 35269888, 2022). "Enhanced levels of autophagy may be related to a tumor-mediated upregulation of cardiac beclin-1 expression and cardiac inflammation (MyD88), which lead to increased cardiac atrophy (FOXO1 signaling)." (PMID 36531941, 2022). "In contrast to those well-described tumor-suppressive activities, the current study reveals that FOXO1 may also act as a pro-oncogenic lineage-survival TF in MCL." (PMID 36282572, 2022). "Therefore, the expression levels of relevant genes were measured; the result showed that FoxO1 was significantly upregulated, while Cyclin D1 was significantly downregulated after mitochondrial inhibition in tumor cells." (PMID 35865479, 2022). "Furthermore, there is a lack of clarity regarding the regulation of mitochondrial respiration in PTC tumor progression through the PI3K/Akt/FoxO1/Cyclin D1 pathway." (PMID 35865479, 2022). "TRPM7 can regulate tumor growth by modulating the AKT/FOXO1 axis." (PMID 35721115, 2022). "Additionally, the manipulation of FOXO1 can regulate the PD-1 axis in the tumor-infiltrating T cells, which are the primary immune effector cells of the TME, indicating a novel therapeutic strategy for cancer treatment." (PMID 36555288, 2022). "Furthermore, the effects of long-term Mito-Fu intake on the levels of TNF-α, pAMPK, FoxO1, and other genes or proteins prompted us to investigate its effects on typical tumor-related pathways." (PMID 35865479, 2022). "To further confirm this observation, we used western blot analyses to assess the expressions of ER, PR, FOXO1, a tumor suppressor located downstream of PR signaling, and insulin-like growth factor-binding protein 1 (IGFBP1), a factor associated with the decidua." (PMID 35717540, 2022). "However, the well-defined tumor suppressor role of FOXO1 has been challenged by recent studies that demonstrated cancer-promoting functions of FOXO in different cellular context." (PMID 35079069, 2022).
tumor (continued). "Another study has also highlighted, HBx-mediated progression of tumour stemness in HCC via a positive feedback loop mechanism involving miR-5188 impairment of FOXO1 (a well-characterized tumour suppressor in HCC) and stimulation of β-catenin nuclear translocation." (PMID 35203390, 2022). "Taken together, these results indicate that FOXO1 exerts a tumor-suppressing effect in HCC cells." (PMID 36359865, 2022). "In addition, Forkhead box O1 (FoxO1) is a key tumor suppressor for cell proliferation, which can control cell cycle and apoptosis and dysregulation of FoxO1 expression has been observed in various cancers." (PMID 36059653, 2022). "FoxO1 mRNA expression decreased during OSCC formation, suggesting that high FoxO1 levels may be adverse for tumor growth." (PMID 33772986, 2022). "By comparison, depletion of FOXO1 by sgFOXO1 resulted in a marked delay in MCL progression and a survival benefit as evidenced by the diminished tumor burden and spleen enlargement, confirming that FOXO1 inhibition could suppress MCL progression in vivo." (PMID 36282572, 2022). "FOXO1 has been shown to inhibit the growth of tumours and can promote apoptosis." (PMID 34905088, 2022). "It was first time we confirmed that MAGI2-AS3 could modulate FOXO1 expression and miR-374a/b-5p play a tumor-promoting role by modulating FOXO1 in HCC." (PMID 36359865, 2022). "FOXO1 is a tumor-suppressing factor that inhibits carcinogenesis." (PMID 36359865, 2022). "Tumor cells-derived miR-135b could suppress expression of FOXO1 transcription factor that regulates gluconeogenesis and glycogenolysis by insulin signaling." (PMID 36147505, 2022). "The expressions of AGK, BCL-2 and FOXO1 were evaluated in tumor tissues of DLBCL patients." (PMID 35910796, 2022). "Dysregulated FOXO1 has been confirmed to function as tumor suppressor in HCC." (PMID 34895065, 2021). "Furthermore, in recent studies, the role of FOXO1 gene as a tumor suppressor in the EMT pathway has been discussed." (PMID 33718760, 2021). "Kan and coworkers suggested that ZBTB20 may promote tumor growth of HCC through transcriptionally binding with the promoter of forkhead box O1 (FoxO1) to repress the expression of FoxO1." (PMID 34680245, 2021). "The forkhead box-O1 (FoxO1) is a central regulator of metazoan physiology and plays a role in cell cycle, proliferation, apoptosis, autophagy, stress resistance, DNA repair, tumor inhibition, metabolism, and other cellular activities." (PMID 34539243, 2021). "To validate this hypothesis, we first analyzed the protein levels of USP7, EZH2 and FOXO1 in human tissue arrays, including a series of paired tumor and adjacent normal tissue samples from the breast, kidney, lung, lymph node, ovary, esophagus and skin." (PMID 33849069, 2021). "Although there is no report of HDAC1 regulating the proliferation or apoptosis of diabetic skin fibroblasts, HDAC inhibitors are often used as a treatment for cardiac fibrosis and tumours, which also shows that it is possible for Ski to regulate FoxO1 through HDAC1." (PMID 33349993, 2021). "Furthermore, lncRNA-MEG3 acts as a tumor suppressor and a ceRNA that regulates E-cadherin and forkhead box O1 (FOXO1) expression by competitively binding to miR-9." (PMID 33422015, 2021). "Interestingly, our study had revealed that this transcription factor FOXO1 can activate 26 disordered tumor suppressor miRNAs to inhibit most carcinogenic genes to promote the survival of HCC patients." (PMID 34307154, 2021). "Recent studies have demonstrated that FOXO1 expression is decreased in BC tissue compared with non-cancerous bladder mucosal tissue and that FOXO1 is associated with a good prognosis and considered a tumour suppressor in BC 11-13." (PMID 33391425, 2021). "In addition, DTL activated JNK through RAC1 and upregulated FOXO1 to induce epithelial–mesenchymal transition, and the migration and invasion of tumor cells." (PMID 34635635, 2021).
tumor (continued). "Finally, our results demonstrate that this key transcription factor FOXO1 can activate a certain number of tumor suppressor miRNAs to improve the survival of HCC patients, suggesting FOXO1 as an effective therapeutic target for HCC patients." (PMID 34307154, 2021). "We therefore determined whether FoxO1 is sufficient to increase FoxP1 transcription and required for its up‐regulation in response to tumour burden." (PMID 33527776, 2021). "In this work, we found that the down-regulated FOXO1 could control 26 down-regulated miRNAs, and at least 10 of them have been reported to act as tumor suppressors in HCC or other cancers." (PMID 34307154, 2021). "When FoxO1 was knocked down, the tumor tissue was more closely packed." (PMID 34539243, 2021). "In many carcinomas, FOXO1 is recognized as a tumor suppressor." (PMID 34511023, 2021). "TFP increases the nuclear localization of FOXO1 to restrict angiogenesis and tumor growth." (PMID 34123834, 2021). "Heterogeneous expression of PAX3:FOXO1 at the single cell level may provide a critical advantage during tumor progression." (PMID 34187933, 2021). "i.e., miR-155, miR-17-92 and miR-21 act as oncogenes by altering the expression levels of MYC, SHIP and FOXO1, respectively, conversely; miR-34a, mir-144 and miR-181a act as tumor suppressors by altering the expression levels of SIRT1, BCL6 and CARD11, respectively." (PMID 34679437, 2021). "Our results validate that FOXO1 acted as a tumor suppressor in PCa and demonstrated that FOXO1 was regulated by miR-142-3p, and miR-142-3p may be a potential target for treatment of PCa." (PMID 32047567, 2020). "The regulatory role of FOXO1 in tumor immunity is equally confusing." (PMID 33584800, 2020). "Furthermore, we localized miR-96-5p and FoxO1 expression, finding that miR-96-5p was predominantly localized in the cytoplasm in all tumor grades and its expression increasing from G1 to G3." (PMID 32766159, 2020). "FOXO1 expression is reduced in most tumors and appears to act as a tumor suppressor gene." (PMID 33584800, 2020). "Finally, a set of target genes of FoxO1 regulating tumor growth and triggering apoptosis (Bim) or inducing cell cycle arrest (p21) were differentially regulated upon treatment with DAC, ENT, or the combination of DAC plus ENT." (PMID 32028599, 2020). "By excluding the possibility that FOXO1 directly mediated tumor progression, we hypothesized that FOXO1 might induce the activation of M2 macrophages to indirectly enhance tumor progression." (PMID 33052231, 2020). "The results showed that the expression of CCL20 was upregulated in FOXO1(+) tumor cells." (PMID 33052231, 2020). "The FOXO1 overexpression often occurred at the tumor margin adjacent to stromal tissues." (PMID 33052231, 2020). "The Venn diagram showed that FOXO1 was upregulated in all three ESCC tumor tissues." (PMID 33052231, 2020). "FOXO1(+) tumor-induced M2 macrophages promoted tumor proliferation via the FAK-PI3K-AKT pathway and the PI3K inhibitor could effectively impede the oncogenical process." (PMID 33052231, 2020). "FOXO1 is constitutively phosphorylated in 85% of the tumor cells of gastric carcinoma samples." (PMID 32629884, 2020). "Additionally, in the co-culture experiment between FOXO1(+)/(-) tumor cells and M0 macrophages, the FOXO1(+) group showed a higher percentage of Ki67(+) tumor cells than the FOXO1(-) group." (PMID 33052231, 2020). "IHC results also showed that FOXO1 was consistently overexpressed at the tumor margin." (PMID 33052231, 2020). "In our previous work, we showed that tumor growth accelerated in myeloid FoxO1 conditional KO mice." (PMID 32973162, 2020). "Criteria for inclusion of patients in prospective clinical trials may be low FoxO1 expression in tumor specimens and resistance to the first-line therapy cisplatin." (PMID 32028599, 2020). "Moreover, FOXO1 has been described to assume a pivotal role in tumor initiation, progression and metastasis." (PMID 32694937, 2020).
tumor (continued). "However, in other malignancies, such as urothelial carcinoma 15, FOXO1 amplification facilitates tumor growth and metastasis, leading to poor prognosis." (PMID 33052231, 2020). "Pharmacological inhibition of CCL20 and CSF-1 or the genetic silencing of FOXO1 might serve as an excellent candidate to suppress tumor progression and improve prognosis." (PMID 33052231, 2020). "Moreover, although we proved reduced glycolysis level and up oxidative phosphorylation level in FoxO1-deficient macrophages, we need more further study on the in vivo effects of FoxO1 on the metabolic switch and the direct consequences for tumor growth." (PMID 32973162, 2020). "We found that CSF-1 expression was significantly upregulated in FOXO1(+) tumor cells." (PMID 33052231, 2020). "The results from this study support the hypothesis that aberrant expression of PLK1 leads to the inhibition of the tumor suppressor function of FOXO1, thereby contributing to PCa survival and/or resistance to therapy." (PMID 32704044, 2020). "The presence of the isoform-specific contributions of FoxO1 and FoxO3 to the tumor-inhibiting and life-extending effects of CR in mice warrants future studies using mice with myeloid-cell-lineage-specific deletion of the Foxo1 or Foxo3 gene under CR conditions." (PMID 32630045, 2020). "FOXO1 is considered as a potential tumor suppressor gene that participates in regulating the differentiation of a variety of cells and plays a role in inhibiting tumor cell proliferation." (PMID 33584800, 2020). "However, FOXO1 knockdown enhanced tumor growth compared with shNS groups and undermined synergistic inhibition of the combined treatment." (PMID 31410199, 2019). "Furthermore, we found that CB is a promising anti-tumor agent that reduced FOXO1-suppressed DDP resistance by antagonizing the FOXO1-interactive protein MYH9 and its-modulated signals in NPC." (PMID 31754475, 2019). "Up-regulated miR-96 and down-regulated FOXO1 was found in tumor tissues and HepG2 cells (P < 0.01)." (PMID 30828264, 2019). "Recent studies have identified an important role of Foxo1 in regulating eTreg cells in tumor." (PMID 31921097, 2019). "In summary, these outcomes imply that prior 2ME + As2O3 treatment attenuates tumour growth efficiently and may suppress OS growth by negatively regulating FoxO1 expression and HIF-1α." (PMID 31905813, 2019). "Furthermore, MYH9 expression restored the signals suppressed by FOXO1, including downregulation of GSK3β protein; however, it did not recover mRNA expression or stimulation of β-catenin and its downstream tumor stemness and EMT signals." (PMID 31754475, 2019). "Now, with data showing progesterone inhibition of tumor growth, it makes it reasonable to perform more detailed mechanistic studies to help define the interaction of nuclear progesterone receptor with nuclear FoxO1 activity in GBM." (PMID 30700763, 2019). "Previous researches demonstrated that increasing FOXO1 level could lead to cell cycle G1 arrest in kinds of tumor cells." (PMID 31223614, 2019). "Our previous study showed that FOXO1-negative cells carry cancer stem-like characteristics in PDAC and affect tumor progression, suggesting that FOXO1 functions as a tumor suppressor in PDAC; however, the underlying mechanism remains unknown." (PMID 31027497, 2019). "Moreover, studies also indicated that FOXO1 enhanced cell apoptosis while tight regulation of FOXO1 was essential for the maintenance of various tumor cells." (PMID 31223614, 2019). "Thus, FoxO1 participates in an autocrine/paracrine loop in preclinical models of drug resistance mimicking the tumor–microenvironment interplay." (PMID 30646603, 2019). "Using U87MG-luc, U87dEGFR and U118MG (grade IV GBM) human cell lines, we examined the effect of progesterone treatments on the expression of Glut1, GAPDH, cytosolic FoxO1 and Phospho-FoxO1 levels, the key players in tumor cell glycolytic metabolism, at 2 and 24 h." (PMID 30700763, 2019).
tumor (continued). "We next investigated whether the expression of FOXO1/CEBPB/NF-κB/CCL20 signaling molecules had prognostic value using tumor tissues from CRC patients." (PMID 31395078, 2019). "Mechanistic analysis indicated that miR-5188 directly targets FOXO1, which interacts with β-catenin in the cytoplasm to reduce the nuclear translocation of β-catenin and promotes the activation of Wnt signaling and downstream tumor stemness, EMT, and c-Jun." (PMID 31695788, 2019). "Likewise, the FOXQ1/NDRG1 axis was shown to exacerbate HCC initiation via enhancing cross talk between fibroblasts and tumor cells, and FOXO1 was reported to contribute to HCC through a different mode of action." (PMID 31615920, 2019). "We showed that FOXO1, 3 and 4 are frequently underexpressed these genes could therefore act as tumour suppressor genes." (PMID 29484124, 2018). "In cancer cells, in response to oxidative stress or serum-starvation, FOXO1 can be acetylated by Sirtuin-2 (Sirt-2), where the acetylated FOXO1 can bind to Atg-7 thereby mediating transcription-independent autophagy and promoting tumour suppression." (PMID 29180117, 2018). "While two tumor suppressor genes, RB1 and FOXO1, are encoded in this region, the precise molecular pathogenesis of these tumors is unknown." (PMID 28887603, 2018). "However, we still know relatively little about the autophagy-related mechanisms of FOXO1 that control the course of tumorigenesis and tumor development." (PMID 29707114, 2018). "Overexpression of miR-186 also repressed the expression of tumor suppressors, including forkhead box O1 (FOXO1), Nuclear Receptor Subfamily 5 Group A Member 2 (NR5A2), and protein phosphatase, Mg2+/Mn2+ dependent 1B (PPM1B) in endometrial, pancreatic, and bladder cancer cells, respectively." (PMID 29653561, 2018). "Besides, a recent study has found that zinc finger protein ZBTB20 promotes tumor growth of HCC via transcriptionally repressing FoxO1." (PMID 28637446, 2017). "FOXO1 may exert its tumor suppression function through its transcription-dependent expression of growth arrest and apoptotic-related genes, including p15, p19, NOXA, FasL, TRAIL, and Bim." (PMID 28099936, 2017). "One of the major unknowns in the study of ARMS is the nature of the cell that originally suffered the PAX3:FOXO1 chromosomal translocation leading to tumour development." (PMID 28615069, 2017). "FOXO1 dysregulation has been observed in several human cancers, and this aberration influences multiple cellular functions, including apoptosis, cell cycle control, DNA damage repair, carcinogenesis, glucose metabolism and tumor immunity." (PMID 27924058, 2017). "Moreover, we identify ATG7 overexpression results in reduction of FOXO1-dependent p27 transcription, thereby inhibiting the tumorigenic growth of BC cells, which highlights the tumor suppressor function of p27 in human BC growth." (PMID 28624205, 2017). "Results showed that resveratrol negatively regulated expression of Ac-FoxO1 and p-FoxO3a (p<0.01), revealing that resveratrol decreased phosphorylation of FoxO3a (by inactivating K-Ras/PI3K/AKT signal) and acetylation of FoxO1 with SIRT1 up-regulation to induce apoptosis in spontaneous neoplasms." (PMID 28903430, 2017). "Since FOXO1 can modulate the synthesis of antioxidant enzymes and it is well known that production of oxidative stress positively regulates tumor growth, we sought to determine if RARRES1 expression could modulate this phenomenon." (PMID 28678839, 2017). "Collectively, these results indicate that ZBTB20 may serve as a prognostic marker and promotes tumor growth of HCC via transcriptionally repressing FoxO1." (PMID 26893361, 2016). "Previous studies have suggested that FOXO1 functions as a tumor suppressor." (PMID 27835585, 2016).